IL4 (interleukin 4)
Diseases named in the same sentence as IL4 in open-access papers (continued):
Sharing a sentence is not in itself a finding about the gene and the disease.
tumor (continued). "Some of these changes are beneficial when it comes to non-tumor-promoting conditions, e.g., the decrease of VEGF, TGFβ, IL6, CXCL1, CXCL9, IL1β, and M2-macrophage-inducing IL4, as well as the increase of immuno-supportive and M1-associated IL12p70 and TNFα." (PMID 34064000, 2021). "To evaluate the effect of IL-4 during CTCL progression from plaques to tumors, we measured the expression of IL-4 in TOX+ cells by comparing tumor and plaque stages." (PMID 34220814, 2021). "Various immunomodulatory cytokines, such as IL4, IL6, and TGF-β, produced by immune cells within the tumor microenvironment promote tumor growth and progression." (PMID 33504001, 2021). "Due to several factors, for example, IL-4 and IL-13, an M2-like differentiation occurs in the TME, which facilitates tumor immune escape and metastasis." (PMID 34359785, 2021). "There is a substantial secretion of IL-4, which recruits TFH, follicular dendritic cells (FDCs), and Tregs that promote tumor growth through BCR signaling and CD40–CD40L interactions." (PMID 33804869, 2021). "We also found that the protein levels of IL-4 and IL-13 of ILC2s from NSCLC tumor tissues were higher than those from NSCLC PBMCs." (PMID 34194433, 2021). "While retroviral transfer of IL-4 did prolong mice survival compared to the control group, it was still significantly less beneficial than introducing the same cytokine using NSCs, suggesting that the intrinsic anti-tumor activity of NSCs may, in part, be responsible for the improvements." (PMID 33668356, 2021). "It was also noted that with the reduction in the Treg cell population, the percentages of Th1 cells (CD4+IFN-γ+) and IFN-γ+ CD8 T cells were increased in tumours, while that of Th2 cells (CD4+IL-4+) was almost unaffected." (PMID 33654093, 2021). "For example, as well as MSCs, ILC2s become suppressive upon activation, and the activated ILC2s produce various cytokines, such as IL4, IL5, IL9, and IL13, to impair the anti-tumor immunity, particularly of NK cells." (PMID 33535613, 2021). "The CD4+ Th cells modulate tumor microenvironment by secreting cytokines such as IFN-γ, TGF-β, IL-4, IL-5, and IL-6." (PMID 33995619, 2021). "To verify the previously reported results, we performed immunohistochemical staining using eight paraffin-embedded tumor tissue samples to investigate the expression of CCL22, GATA-3, and IL4." (PMID 34391381, 2021). "In the tumor stage contrasts for STAD and COAD, we see Th2 and NK cells expressing inflammation related genes IL1A, IL1B, IL4, and TNF." (PMID 34512714, 2021). "The M2a phenotype is induced when TAMs are stimulated with IL-4 and/or IL-13, and they will produce high amounts of IL-10 and TGF-β that exert tumor-promoting activities." (PMID 34207168, 2021). "In this experiment, lycopene managed to enhance IFNβ, IFNγ, IRF1, IRF7, CXCL9, CXCL10 while suppressing IL-4, IL-10, DMNT3a, methylation of IRF1, IRF7 promoters and most importantly, the tumor volume." (PMID 34202203, 2021). "Strikingly, even in a tumor lesion where the percentage of TOX+ cells was high at the basal level (40%), culturing with IL-4 still increased the expression of TOX and the percentage of TOX+ cells (67.2%)." (PMID 34220814, 2021). "Further, cytokines including IL-4, TGF-β, IL-17, VEGF, PDGF, M-CSF, and MMPs secreted by TAM-M2 (Coffelt, Hughes & Lewis, 2009) are involved in tumour invasion, metastasis, angiogenesis, and lymphangiogenesis." (PMID 34141479, 2021). "IL-4 gene transduced MC38 murine CRC cell line promoted a Th1-type response and tumor-specific immune responses in B6 mice." (PMID 33450900, 2021). "In the tumor, they differentiate into anti-inflammatory M2-like TAM by tumor and TME-derived factors like M-CSF, IL-4, IL-10, and TGF-β." (PMID 34795675, 2021).
tumor (continued). "On the other hand, M2 macrophages are mainly differentiated from TAM by stimulating interleukin (IL)-4, IL-13, prostaglandin E2 (PGE2), or transforming growth factor (TGF)-β, which is reported to promote the proliferation and metastasis of tumor cells." (PMID 34506209, 2021). "Combined vaccination inhibited tumor progression compared with chitosan or IL-12 alone.Co-formulation of chitosan and IL-12 resulted in higher IFN-γ and IL-4 and decreased IL-10 generation." (PMID 33816349, 2021). "At the same time, CCL17 attenuates MDSCs via a pathway including IL-4 and CXCL17, downregulating tumor formation." (PMID 33670758, 2021). "In the tumor microenvironment (TME), IL‐4 elicits an increased Th2 response and activates myeloid‐derived suppressor cells (MDSCs) and tumor‐associated macrophages (TAMs), both of which express the IL‐4R, to promote immunosuppression and angiogenesis." (PMID 33682324, 2021). "While most studies suggest that diverse NKT cells inhibit anti-tumour immunity, iNKT cells contribute to natural tumour surveillance with immediate cytokine secretion (IFN-γ, TNF, IL-13, IL-17, IL-4, IL21, IL-22) and FasL/TRAIL pathways." (PMID 33499101, 2021). "After 24-h co-incubation of tumor cells and effector T cells at an E:T ratio of 10:1, B7-H3 CAR-T cells produced significantly higher amounts of IFN-γ, TNF-α, IL-2, IL-6, IL-4 and IL-10 in the culture supernatants compared with vehicle T cells." (PMID 33514401, 2021). "The expression levels of CD163 and CD206 in THP-1 cells recovered from co-culture with CHS were quite comparable to those assessed in PMA/IL-4 -treated THP-1, suggesting a tumor-promoted differentiation/polarization towards M2-like macrophages." (PMID 32344648, 2020). "CSCs recruit macrophages to the tumor niche by producing pro-inflammatory cytokines and chemokines, such as CCL2, IL-6, IL-4, VEGF and TGF-ß." (PMID 33059744, 2020). "Still, the observations made at mRNA level were in opposition to those made for IL-4 protein, as its protein concentration was significantly higher in CRC than GC, both for tumor and adjacent tissue." (PMID 32512917, 2020). "A variety of cytokines released by MCs including IL-1, IL-4, IL-8, IL-6, MCP-3, MCP-4, TNF-α, IFN-γ, LTB4, TGF-β, and chymase contribute to developing inflammation, inhibiting tumor cell growth, and inducing tumor cell apoptosis." (PMID 31256327, 2020). "Only SFV4-infected tumor cells consistently induced DCs to secrete Th1 cytokines (IFN-γ, IL-12, TNF-α), Th2 cytokines (IL-4, IL-13), proinflammatory cytokines (IL-6, IL-8, IL-1β,) and anti-inflammatory cytokine (IL-10)." (PMID 31969562, 2020). "Cytokines, like IL-10, IL4, IL-6, and TGF-β, released by these cells can inhibit both innate and adaptive immunity and can also directly promote tumor progression." (PMID 32595757, 2020). "Accordingly, our analysis of a subset of genes that had a significant Z score for similarity to proliferation of tumor cells predicted cell cycle progression through genes such as CDK4, HRAS, IL-4, CSF2, IFNG, IL-6 and STAT3." (PMID 33180876, 2020). "Th2 cytokines such as IL-4, IL-10, and IL-13 are able to induce M2 macrophages which have reduced cytotoxic activity and dampens CD8 T cell-mediated anti-tumor activity." (PMID 33117354, 2020). "Our data suggest that higher expressed ICOSL tumor tissues express higher levels of IFN-γ and IL-17, and less IL-10 and IL-4, compared with ICOSL low expressed tumor tissue, indicating that ICOSL promotes Th1 and Th17 response in NPC patients." (PMID 31998801, 2020). "Widespread cell death in breast cancer during postpartum involution triggers wound-healing cytokines, including IL-4, IL-13, and IL-10, in the TME to promote metastatic tumor progression." (PMID 32346605, 2020). "Specifically, tumor tissue supernatants from WT and GCSFR−/− mice tumors were assessed for the production of IFNγ, IL-10, IL-17A, and IL-4, which are considered general markers of Th1, Tregs, Th17, and Th2 cells, respectively." (PMID 33042110, 2020).
tumor (continued). "The Th2 marker cytokine IL-4 promoted the proliferation of human pancreatic cancer cells and enhanced the activation of STAT3, AKT, and MAPK pathways, suggesting direct tumor-promoting activity." (PMID 33022971, 2020). "Finally, in the injured muscle of C26 hosts treated with IL4 and analysed around 25–31 days after injury, the number of mature fibres characterized by peripheral nuclei was higher than in untreated injured C26‐bearing mice (that died 13 days after tumour transplantation and 8 days after CTX injury)." (PMID 32103619, 2020). "Interleukin‐4 (IL‐4) secreted by tumor cells and CD4+ T cells polarizes TAMs to an M2 phenotype and enhances tumor cell growth, invasion, and metastasis." (PMID 34766109, 2020). "In tumors, IL-4, IL-13, IL-10, TGF-β, and CXCL5 increase tumor cell growth and metastasis through efferocytosis-induced cell clearance and macrophage polarization in the TME." (PMID 32346605, 2020). "MCs through releasing IL-1, IL-4, IL-6, and TNF-α can actively participate in the elimination of tumor cells and rejection of tumors." (PMID 31256327, 2020). "Tumor-infiltrating T, B, and NK cell levels and plasma concentrations of Th1 (IL-2, IFN-γ, and TNF-α), Th2 (IL-4, IL-5, IL-6, and IL-10), Th9 (IL-9), and Th17 (IL-17A, IL-17F, IL-21, and IL-22) cytokines were evaluated." (PMID 32802733, 2020). "Deregulation of genes important in immune responses, such as IL‐4 and IFN‐β, promotes tumour growth, invasion, metastasis and chemotherapy resistance." (PMID 32969187, 2020). "Regarding MCP-1, IL-4 and MCP-1 are reportedly involved in a “self-amplifying loop” in tumor microenvironment, whereby interleukin promotes MCP1 expression by endothelial cells, which, in turn, induces Th2 differentiation by up-regulating IL-4 synthesis." (PMID 32512917, 2020). "TNFα, MCP-1 and IL-10, which we previously reported to be enhanced in the tumour microenvironment following systemic IgE treatment in vivo, were secreted by monocytes alongside immune mediators CXCL-10, IL-4, IL-1β and IL-23." (PMID 33203088, 2020). "What's more, Xue and colleagues reported that IL-1β combined with IL-4, in the absence of TGF-β, induced a non-canonical Th9 subset that was less exhausted and showed superior anti-tumor effects to classic Th9 cells induced by TGF-β and IL-4." (PMID 32508847, 2020). "This rejection was mediated through IL-4 expressing B-cells, TNF-α-expressing CD11b+GR1hi myeloid cells, and a reduction of tumor-promoting Th17 cells." (PMID 33266109, 2020). "TAMs originate as blood monocytes recruited from the tumor vasculature by tumor-derived signals, such as M-CSF, MCP-1, IL-4, and VEGF." (PMID 32487125, 2020). "We compared the methylation status of the NT5E gene according to the expression of inflammatory markers including TNF-α, IL-4, NF-κB p50, CD4+, and CD8+ T cells, CD68+ macrophages, intratumoral and peritumoral inflammation in tumor tissues." (PMID 33198064, 2020). "Because IL4, IL13, IL10, and CSF-1 are stimuli in M2 differentiation as reported in previous studies 6, 20, we performed qRT-PCR in FOXO1(+) and FOXO1(-) tumor cells to detect the expression of these genes." (PMID 33052231, 2020). "Monocytes were differentiated and polarized into TAM using tumor-conditioned media (TCM) from breast cancer or lymphoma tumor cells and a cytokine cocktail consisting of IL-4, IL-10, and M-CSF." (PMID 31138333, 2019). "IL4 and IL13 also play crucial roles in tumor biology and tumor immunology via activation of immune cells in the tumor microenvironment." (PMID 31540495, 2019). "Of these molecules, IL-1β, IL-6, TNF-α, and IL-4 promote the phosphorylation of downstream proteins, e.g., NF-κB and STAT3, which then lead to inflammation, tumor proliferation, and prevention of apoptosis in cancer." (PMID 31781219, 2019). "After being repeatedly challenged with IL4-Huh7 cells, 4/21 ICR-CAR T cells displayed an improved tumor-cell elimination than the control CAR and 4/7 ICR-CAR T cells." (PMID 31379876, 2019).
tumor (continued). "Hypoxia, colony stimulating factor 1 (CSF-1), TGF- β, IL-4 and IL-13 are able to enhance the switch of TAM from M1 to M2 phenotype, thus changing the M1/M2 ratio while tumor progression." (PMID 30680411, 2019). "Despite being less established, B cells can also activate an antigen presentation phenotype and play a role in driving anti-tumor responses upon engineering with chimeric IL-2 and TGF-β or IL-4 and GM-CSF." (PMID 31921109, 2019). "Altogether, in the presence of the inhibitory IL-4 signal, CAR-T cells expressing 4/21 ICR polarized into Th17-like phenotypes and showed potent anti-tumor effects and long-term persistence in vivo." (PMID 31379876, 2019). "The investigators demonstrated in a preclinical pancreatic model, known for high IL-4 expression within the TME, that ICR CAR T cells have enhanced anti-tumor activity, increased expansion, and persistence." (PMID 30736355, 2019). "Upon IL-4 stimulation, 4/21 ICR activated the STAT3 pathway and promoted Th17-like polarization and tumor-targeted cytotoxicity in CAR-T cells in vitro." (PMID 31379876, 2019). "Then, the production of different cytokines (IFN-γ, IL-4, TNF-α and IL-17-A) by peripheral immune cells was evaluated at different time points after tumour irradiation." (PMID 31906092, 2019). "In the IL-4-PLC/PRF/5 tumor model, CAR-T cells were challenged with a larger tumor burden (~200 mm3)." (PMID 31379876, 2019). "PD-L1 upregulation can be motivated by cytokines induced by tumor-infiltrating immune cells, including interferon (IFN), tumor necrosis factor (TNFalpha), interleukin (IL-4), and vascular endothelial growth factor (VEGF) etc.." (PMID 31039792, 2019). "By contrast, alternatively activated macrophages or M2 macrophages are polarized by anti-inflammatory signals, such as IL10, IL4, and IL13 and are involved in immunosuppression, tumor invasion, tumor growth, angiogenesis and metastasis." (PMID 31096567, 2019). "For instance, dihydroartemisinin was reported to inhibit tumor tissue, increase the level of interferon-gamma (IFN-γ), and decrease interleukin 4 (IL-4) in tumor-bearing mice." (PMID 31892257, 2019). "Tumor tissues from DTT-neoAg-treated mice expressed markedly higher levels of IFN-γ and IL-4 than PBS-treated mice while the levels of IL-12 and IL-10 were similar." (PMID 31749795, 2019). "It has been reported that IL4 and IL13-mediated signaling pathways play an important role in tumor biology." (PMID 31540495, 2019). "The tumor clearance was accompanied by the higher expression immuno-modulating cytokines such as IFN-γ, interleukin (IL)-4, and IL-17 cytokines in the transferred T cells." (PMID 29473868, 2018). "The tripartite peptide when combined with CpG induced T cell responses as measured by IFNγ and IL4 ELISpot analysis, in vivo CTL and protected mice from a tumour challenge." (PMID 30200528, 2018). "Umbelliprenin treatment in both tumor-bearing mice and control normal mice showed significantly increased IFN-γ and decreased IL-4(P < 0.05)." (PMID 30127820, 2018). "In the PDAC microenvironment, cytokines including G-CSF, GM-CSF, IL-1β, IL-4, IL-6, prostaglandin E2 (PGE2), IFN-γ, and VEGF induce MDSCs to infiltrate the tumor." (PMID 30662458, 2018). "To interrogate protein-level status of the IL-4 signaling axis in DIPG, we performed IHC analysis of a cohort of formalin fixed paraffin embedded DIPG tumor tissues." (PMID 29621254, 2018). "TNF, IL6 and ANGPT2 were expressed equally by both DLD1 and SKBR7 xenografts, whereas higher levels of IL1B, IL4, IL13 and VEGFA were found in DLD1 tumours." (PMID 29367702, 2018). "IL-10 and IL-4 suppress the local immune response and mediate the recruitment of regulatory T cells and TAM in the tumour microenvironment." (PMID 30539028, 2018). "But, the level of IL-10, a Th2 cytokine, was significantly higher in the tumor microenvironment of wild type mice that developed invasive SCC, and only relatively low concentrations of IL-4 and IL-13 were detected." (PMID 30112116, 2018).
tumor (continued). "Tumor samples obtained from ST2KO mice presented lower levels of IFN-γ, TNF-α, IL-10, and IL-17, while the production of IL-12, IL-4, IL-13 and TGF-β was similar between tumor skin samples obtained from wild type and ST2KO mice." (PMID 30112116, 2018). "Tumor size, serum levels of IFN-γ and IL-4 by ELISA, and Ki-67, MMP2, MMP9, VEGF and E-cadherin markers by IHC method were evaluated." (PMID 30127820, 2018). "We further detected 20 serum cytokines in tumor-bearing mice and 7 cytokines were significantly different between GLE treated and model groups, including IFN-γ, IL-1β, IL-4, IL-9, IL-12, RANTES and TNF-α." (PMID 30139984, 2018). "The mRNA level of IL4 and IL10 was significantly decreased in PKN2-WT tumor cells, but increased in PKN2-K686R tumor cells, indicating that IL4 and IL10 are negatively regulated by PKN2." (PMID 29368606, 2018). "This study established down-regulating expression of membrane antigens that are indicative of the activation, differentiation, and maturation of tumor Jurkat T cells (CD3, CD4, CD8, and CD95) and reducing the secretion of IL-4 and TNFα." (PMID 29495627, 2018). "However, since the IL-4 DC vaccine only weakly recruits γδ T cells and generally fails to potentiate γδ T cell functions, this missing interaction could aid to optimize DC vaccine immunopotency, promoting cytotoxic and long-lasting anti-tumor immunity." (PMID 29692776, 2018). "In support of this idea, deletion of IL-4 in Tbkbp1-KO mice, which blocked hyper-production of memory-like CD8+ T cells, abrogated their ability to mediate stronger tumor rejection and CD8+ effector T cell responses." (PMID 30022064, 2018). "Briefly, IL-12, IL-17, GM-CSF, MIP-1α, IL-5, IFN-γ, IL-1Rα, IL-7, IP-10, IL-2R, IL-4,IL-15,MIP-1β levels were higher in the inflammation group and kept relative lower level in healthy and tumor groups." (PMID 28977824, 2017). "Uptake of these exosomes by recipient cells caused increased secretion (2–6 fold) of specific cytokines (Interleukin-4, Stem Cell Factor, Platelet-derived Growth Factor-B), depending on the TGFBR2 expression status of the tumor cell." (PMID 28376875, 2017). "Tumour‐derived mediators, such as TGF‐β, IL‐1β and IL‐6, as well as cytokines produced by T cells, such as IFN‐γ, IL‐4 and IL‐10, promote MDSCs population expansion and support their immunosuppressive activity." (PMID 28276625, 2017). "There is evidence that the processes of tumor promotion, progression, and metastasis are governed by select Th cell subsets, including IFN-γ-producing Th1 cells, IL-4-producing Th2 cells and IL-17-producing Th17 cells." (PMID 29245934, 2017). "The breadth of responses includes anti-tumor effector (Granzyme B, IFN-γ, MIP-1α, TNF-α), stimulatory (GM-CSF, IL-2, IL-8), regulatory (IL-4, IL-13, IL-22), and inflammatory (IL-6, IL-17A) functions." (PMID 29157295, 2017). "Let x, y, and z denote tumor cells, CD4+ T cells, and antitumor cytokine (IL-4 or any antitumor cytokine produced by Th2), respectively." (PMID 29250133, 2017). "We cover fundamental molecular players in the tumor microenvironment including extra- (CCL2, CSF-1, CXCL12, IL-4, IL-13, semaphorins, WNT5A, and WNT7B) and intracellular signals." (PMID 28197019, 2017). "Serum CCL2, IL-10, IL-5, IL-4, TNF-α, IL1-β and IL-12p70 levels increased with age irrespective of parity status, but were specifically reduced following OC tumor induction only in multiparous mice." (PMID 28966800, 2017). "Also, the number of IFN-γ-secreting cells were significantly expanded compared with IL-4-secreting cells in the LM4Δhly::E7-immunized group (**P < 0.01), which demonstrated that the immune response induced by LM4Δhly::E7 is skewed toward a Th1 type response in tumor-bearing mice." (PMID 28706878, 2017).